SIRT1 (sirtuin 1)
Diseases named in the same sentence as SIRT1 in open-access papers (continued):
Sharing a sentence is not in itself a finding about the gene and the disease.
cancer (continued). "SIRT1 also regulates cellular proliferation and migration, which has an inhibitory influence on the progression of cancer." (PMID 39479446, 2024). "It is noteworthy that the FOXO3-associated signaling pathways have been recognized as therapeutic targets for various cancers, and our research findings provide a novel mechanistic understanding of SIRT1 as an upstream regulatory factor." (PMID 39266959, 2024). "Given that tNOX contributes to regulating SIRT1 activity, we propose that tNOX targeting is a better operational strategy for reducing cancer growth in both in vitro and in vivo studies." (PMID 38567911, 2024). "We systematically examined the role of SIRT1 in pan-cancer by analyzing data from The Cancer Genome Atlas (TCGA) and Genotype-Tissue Expression (GTEx) databases." (PMID 39845948, 2024). "We analyzed the differential expression of SIRT1 in different immune and molecular subtypes in pan-cancer." (PMID 39845948, 2024). "In contrast, pure deletion of the Sirt1 gene triggers the apoptotic pathway, increases cell death, and decreases autophagy and cancer formation." (PMID 38214831, 2024). "AMPK acts as a regulator of autophagy in various cancers, with growing evidence suggesting that SIRT1 serves as an upstream mediator of AMPK in this role." (PMID 39403142, 2024). "Overall, our study provides a series of novel insights into the role of SIRT1 in EC, indicating its central regulatory role in the development of this cancer." (PMID 39266959, 2024). "Its substrates encompass proteins that influence chromatin folding, metabolic control, and stress responses, linking SIRT1 to aging, cancer, cardiovascular diseases, and neurodegenerative disorders." (PMID 37676057, 2024). "Elevated levels of miR-6068 have been observed in PC-3 and CWR-R1ca cell lines, where it promotes aggressive cellular phenotypes by inhibiting the hypermethylated in the cancer 2 (HIC2)/SIRT1 axis." (PMID 39796040, 2024). "While reports on the association between SIRT1 and hormone treatment response in other cancers exist, we have made the novel discovery that changes in SIRT1 activity significantly affect the tumor's response to hormones in EC." (PMID 39266959, 2024). "SIRT1, commonly recognized as a proto-oncogene in various cancers, is known for its involvement in promoting cell survival and proliferation." (PMID 38794205, 2024). "In this study, we found that SIRT1 plays a critical role in the growth of EC, which is consistent with previous reports on SIRT1 in other cancers." (PMID 39266959, 2024). "SIRT1 expression is significantly correlated with immune regulatory factors across various cancer types." (PMID 39845948, 2024). "Early studies primarily focused on the relationship between SIRT1 and cellular aging, survival, and metabolism regulation, while its specific function in certain cancers remains controversial." (PMID 39266959, 2024). "Some studies have shown varying SIRT1 responses across tissue types and cancer models, indicating the need for further research on SIRT1 modulation by NAM in AK patients." (PMID 39766219, 2024). "Our study provides a solid foundation for understanding the role of SIRT1 in cancer and provides valuable insights for the development of future precision targeted therapies and immunotherapies." (PMID 39845948, 2024). "By preventing SIRT1 from deacetylating key regulators of apoptosis and cell death, these inhibitors can sensitize cancer cells to treatment, overcoming resistance and leading to more effective cancer eradication." (PMID 39403142, 2024).
cancer (continued). "There are various types of sirtuins, with SIRT1 being particularly well-studied for its dual role in cancer progression and inhibition." (PMID 39403142, 2024). "In summary, this study provides compelling evidence supporting the oncogenic role of SIRT1 across multiple cancers and highlights its promising potential as a therapeutic target for cancer treatment." (PMID 39845948, 2024). "SPC-180002, a novel dual inhibitor of SIRT1/3, disrupts redox homeostasis and mitochondrial function, leading to cell cycle arrest and strong inhibition of cancer cell growth." (PMID 39403142, 2024). "SIRT1 promotes the epithelial–mesenchymal transition (EMT) process in cancer while endowing more aggressive traits to cancer but decreasing the antioxidant system." (PMID 37107292, 2023). "Previous cancer research has revealed an intriguing positive feedback loop between SIRT1 and c-Myc that is crucial in tumorigenesis." (PMID 37554307, 2023). "Previous studies have shown that SIRT1 is dysregulated in various types of cancer, including lung cancer, and can affect cancer cell proliferation, survival, and migration." (PMID 37670258, 2023). "Inhibition of SIRT1 resulted in decreased viability and migration of cancer cells as well as a reduction in tumor volume and growth rate." (PMID 37630770, 2023). "It is likely that, in these cells as well as in cancer cells, the increased S1P accumulation induced by acidosis can result in higher Sirt1 expression on the one hand and the inhibition of HDAC1/2 on the other, although this has never been demonstrated." (PMID 36982369, 2023). "The participation of SIRT1 in drug resistance in different types of cancer has been observed via drug metabolism, apoptosis induction, DNA damage, and repair or autophagy." (PMID 37833921, 2023). "Contrary to the expected oncogenic roles of Notch1 and c-Myc, the biological functions of SIRT1 in cancer remain controversial." (PMID 37960146, 2023). "SIRT1-7 have the ability to function as both oncosuppressors and oncopromoters, contingent upon the particular type of cancer and the intracellular signaling pathways involved." (PMID 37175631, 2023). "SIRT1 has also been widely studied as a cancer gene in other tissues, especially in cancerous tumors of the liver, oral cavity, and bladder, and has been reported to have potential as a cancer therapeutic target." (PMID 36975503, 2023). "Resveratrol oligomers, including vitisin A, (−)-vitisin B, and (+)-hopeaphenol, have been found to have promising anti-cancer properties due to their ability to inhibit the activity of the human SIRT1 enzyme." (PMID 37242510, 2023). "Zheng and his colleagues demonstrated that metformin activates the AMPK/SIRT1/NF-κB pathway, leading to the induction of cell pyroptosis, and thus exerting an anti-cancer effect." (PMID 37175631, 2023). "Studies have delineated the multifaceted role of SIRT1 in different stages of cancer, including its involvement in genome instability, tumor initiation, proliferation, metabolism, and therapeutic responses." (PMID 38117829, 2023). "We also show that SIRT1 deacetylase activity mediates the anti-proliferative action of 1,25(OH)2D3 in CRC, which is in line with the recent proposal that SIRT1 activity opposes several cancer cell hallmarks." (PMID 37530744, 2023). "Since NAD+ metabolism is composed of cADP-ribose synthases, ADP-ribosyltransferases and sirtuins such as Sirtuin 1 (SIRT1) are elevated in response to visfatin in cancer stem cells (CSCs)." (PMID 36830834, 2023). "For instance, SIRT-1, a histone deacetylase is clinically observed to play a contributing role in the pathogenesis of many cancers." (PMID 37149609, 2023).
cancer (continued). "SIRT-1, which is typically localized to the nucleus in cancer cells, forms a molecular complex with three proteins essential for autophagy initiation: ATG-5, ATG-7, and LC3." (PMID 37850626, 2023). "While SIRT1 has been explored in depth, future research is prompted regarding its roles in other disease processes, such as cancer." (PMID 37456463, 2023). "In cancer cells, the incidence of R-loops, as well as the frequency of replication initiation events, increased when SIRT1 activity declined." (PMID 37998365, 2023). "Recently, SIRT-1 has been stated as an oncoprotein in a variety of cancers, including lymphoma, breast, lung, ovarian, pancreatic, and bladder cancer." (PMID 37149609, 2023). "Several studies have presented that SIRT1 can function as a tumor promoter or tumor suppressor depending on its targets in specific cancer and signaling pathways." (PMID 37671046, 2023). "For instance, sumoylation of SIRT1 promotes the survival of normal and cancer cells, while sumoylation of protein peroxiredoxin 6 impairs its cell protective function." (PMID 37828576, 2023). "Melatonin in addition to simple laser treatment was able to boost the antitumor cancer activity impairing the tumor microenvironment, increasing the collagen structure around the tumor, and modulating the altered SIRT1 pathways." (PMID 37894275, 2023). "In particular, SIRT1 is known to control the activity of HIF-1α under hypoxic condtions in various cancers." (PMID 37777750, 2023). "In contrast, the silencing of SIRT1 by siRNA reduced the frequency and invasion and migration ability of cancer cells." (PMID 37490168, 2023). "The epigenetic factor SIRT1, known to regulate different aspects of homeostasis and cancer, plays an important role in normal and neoplastic hematopoiesis." (PMID 37833921, 2023). "Lactate stimulates the sirtuin 1 (SIRT1)/PGC-1 axis in cancer cells, leading to increased mitochondrial bulk and activity." (PMID 36769263, 2023). "MiR-217/SIRT1 interaction has been studied in various types of cancer including hepatocellular carcinoma, osteosarcoma and colorectal cancer." (PMID 38136977, 2023). "The role of SIRT1 in cancer, including PTC patients, has been extensively studied over the past decade." (PMID 37173902, 2023). "Intriguingly, the PGCCs derived from Cal33 and FaDu cells had shown SIRT1 downregulation as compared to parent cancer cells." (PMID 37949849, 2023). "Understanding how SIRT1 influences the response of cancer cells to chemotherapy, especially drugs like cisplatin, is crucial." (PMID 38203666, 2023). "The pharmacological inhibition of SIRT1 in all cell types and a genetic deactivation of SIRT1 in cancer cells triggered excess DNA synthesis via the initiation of DNA replication from dormant origins." (PMID 37998365, 2023). "Nevertheless, the promotion of PPARγ-dependent SIRT1 expression in HeLa cancer cells would certainly lead to higher cancer cell viability." (PMID 37762053, 2023). "The main negative regulator of autophagy is PI3K/AKT/mTOR signaling, and potential stimulators in normal and cancer cells include sirtuin 1 (SIRT1) and 5′ adenosine-monophosphate-activated protein kinase (AMPK)." (PMID 36835075, 2023). "miR-22, miR-93, miR-217 and miR-449 also suppress SIRT1 to control cancer genesis by inhibiting cell proliferation and stimulating cellular aging." (PMID 37175631, 2023). "SIRT1 is significantly expressed in HCC cell lines and tumor tissues and facilitates metastasis, while pharmacological SIRT1 activation was found to limit cancer growth in mouse models." (PMID 37715252, 2023).
cancer (continued). "Regarding molecular mechanisms of BC progression, SIRT1, as a crucial regulator of cellular targets, is the most studied sirtuin with a promising therapeutic potential for many diseases like cancer, concretely BC." (PMID 36771230, 2023). "Consistently, NAMPT and SIRT1 levels have been seen to rise in HCC and other cancers, a condition linked to a bad prognosis for those who have the disease." (PMID 36899911, 2023). "Insulin‐like growth factor 2 mRNA‐binding protein 2 (IGF2BP2) is a widely studied RBP, and sirtuin 1 also known as SIRT1 has been reported to be involved in cancer progression." (PMID 36510377, 2023). "As mentioned, potential stimulators of autophagy in normal and cancer cells include SIRT1, which affects the regulation of the mTOR pathway." (PMID 36835075, 2023). "In this paper, we found that ursolic acid (UA) alleviated cancer cachexia and prevented muscle wasting via activating SIRT1, and thence inhibiting phosphorylation levels of NF-κB and STAT3." (PMID 37190306, 2023). "NNMT1 reinforces chemoresistance by stabilizing the SIRT1 protein, which plays a crucial role in cancer drug resistance, including apoptosis inactivation." (PMID 36829149, 2023). "To delve into the role of SIRT1, we used Ex-527 and assessed its effects on muscle wasting and cancer cachexia in vivo." (PMID 37190306, 2023). "Subsequently, Sirt1 has been widely studied as a cancer gene because of its unique role in transcriptional silencing, cell cycle progression, and chromosome stability." (PMID 36975503, 2023). "As an upstream target of DNM1L, SIRT1 regulates the mitochondrial dynamics for cancer cell survival during chemotherapeutic stress." (PMID 37949849, 2023). "Our results showed a decrease in SIRT1 expression from normal mammary gland tissue, and from benign and well-differentiated malignant tumors (G1) to less differentiated ones (G2–G3)." (PMID 37627400, 2023). "The single-cell RNA sequencing data and gene expression profiling interactive analysis (GEPIA; gepia.cancer-pku.cn) suggested that SIRT1 is upregulated under stress conditions to promote FAO." (PMID 37063423, 2023). "Small molecule SIRT1 inhibitors have been reported to show potential as anti-cancer drugs by inducing cancer cell death." (PMID 37242510, 2023). "SIRT1 has a dual role in tumorigenesis, acting as both tumor suppressor and oncogene depending on the cancer type and stage." (PMID 37715252, 2023). "More recently, SIRT1 has been reported to be a critical regulator for cell metabolism in cancer development and progression." (PMID 37627400, 2023). "The positive feedback loop between SIRT1 and c-Myc has been reported to suppress senescence and apoptosis in established cancer cells." (PMID 37554307, 2023). "SIRT1 acts as a suppressor of cancer cell migration by impeding the EMT process both in vitro and in vivo." (PMID 37670258, 2023). "Drug resistance is a multifactorial cancer complication explained by the deregulation of epigenetic actors such as SIRT1, among other molecular mechanisms." (PMID 37833921, 2023). "Collectively, these results indicate that the SIRT1 inhibitor EX527 has potential as an adjuvant therapy for reducing chemoresistance in KRASMut-driven cancers." (PMID 37779142, 2023). "The activation of AMPK promotes autophagy and mitochondrial biogenesis by inhibiting mTOR, while SIRT1 inhibits the nuclear factor kappa-light chain enhancer of activated B cells (NF-κB), resulting in anti-inflammatory and anti-cancer effects." (PMID 37630770, 2023). "In conclusion, we found that UA alleviates cancer cachexia and prevents muscle wasting via activating SIRT1, and thence inhibiting phosphorylation levels of NF-κB and STAT3." (PMID 37190306, 2023).
cancer (continued). "The molecular link between miRNAs, SREBPs, and SIRT1 (an oncogene closely related to tumorigenesis) in cancer is a topic of much focus." (PMID 36969840, 2023). "SIRT1 is an NAD+-dependent epigenetic modifier whose activity is classically associated with healthy aging and longevity, but its function in cancer is not well understood." (PMID 37530744, 2023). "All well-differentiated (G1) carcinomas (12/12; 100%) displayed strong SIRT1 immunoreactivity (mean IR score = 6.16 ± 0.936, range 2–12) and nuclear immunostaining, even if a moderate cytoplasmic reactivity was found in some neoplastic cells." (PMID 37627400, 2023). "It was observed that SIRT1 expression was remarkedly higher in the cancer tissue in comparison to the adjacent normal ovarian tissue (P = 0.0003)." (PMID 35496046, 2022). "In cancer, SIRT-1 has a controversial role, being reported with oncopromoter and oncosuppressor functions." (PMID 36080416, 2022). "The class III deacetylase SIRT1, a member of the sirtuin protein family, plays a critical role in a variety of cancers." (PMID 35183223, 2022). "Elevated SIRT1 expression is detected in various cancer tissues and cancer cell lines, such as leukemia and prostate cancer 53,54." (PMID 35069908, 2022). "SIRT1 was generally known as an oncogene and involved in multiple cellular processes including cell cycle, apoptosis, and cancer metastasis." (PMID 35136826, 2022). "In cancer cells, inhibition of SIRT1/2 has been reported to induce pro-survival autophagy via acetylation of HSPA5." (PMID 35269765, 2022). "Future investigations are warranted to illustrate under which conditions SIRT1-regulating lncRNAs perform an enhancive or suppressive action on cancer cell pyroptosis." (PMID 36387211, 2022). "Among the seven members of the sirtuin family, SIRT1 is the most extensively studied in the cancer types as there are conflicting evidences regarding the association of SIRT1 and tumorigenesis." (PMID 35496046, 2022). "With regard to SIRT1, its role in cancer remains controversial, although its overexpression has been associated with poor prognosis in several cancer types." (PMID 36293105, 2022). "SIRT1 antagonizes macrophage inflammation and cancer induced by chronic inflammation by increasing SIRT1 activator NAD+ and inhibiting HMGB1 release." (PMID 36081910, 2022). "Most reports and studies are based on SIRT1 in GC, but the functions of the six other sirtuins are now emerging, including curiosity—do other sirtuins also have this dual role (like SIRT1), or can they perhaps switch from cancer promotor to suppressor?" (PMID 36499440, 2022). "Overall, clinical studies investigating the therapeutic potential of SIRT1 in cancer treatment hold promising results, proving the antitumor activity of SIRT1 modulators in BC." (PMID 35927590, 2022). "Effects on immune responses, autophagy, and inflammation were also observed in published studies to illustrate the mechanism of SIRT1 on cancer cell proliferation, metastasis, and apoptosis." (PMID 35350833, 2022). "Given that the acetylation levels of various proteins impact many cellular functions, we further explored the functional significance of tNOX-modulated NAD+ and NAD+-dependent deacetylase, SIRT1, in cancer cells." (PMID 36230644, 2022). "However, these suggest that defects in resolving transcriptional regulatory G4s cause transcriptional alterations in many genes, among which a certain gene, such as SIRT1, may be associated with a cell type-specific phenotype as a context-dependent cancer driver." (PMID 35327946, 2022).